PROS1 (protein S)
Diseases named in the same sentence as PROS1 in open-access papers (continued):
Sharing a sentence is not in itself a finding about the gene and the disease.
thrombophilia (continued). "For example, COL2A1 mutations weaken the strength of the epiphyseal cartilage matrix, mutations in Factor V Leiden, and deficiencies in Protein-C and Protein-S contribute to thrombophilia, while nitric oxide synthase and IL-6 gene polymorphisms potentially affect endothelial cell function." (PMID 40041162, 2025). "Regarding recurrence-mediated pathways, beyond amplified thrombin generation or impaired fibrinolysis, patients with major congenital thrombophilia (protein C, protein S, or antithrombin deficiencies) experience higher rates of recurrent VTE, including clinically silent events." (PMID 41007777, 2025). "Thrombophilia workup revealed elevated antiphospholipid IgM antibody and deficient protein S. Protein S is required for the degradation of coagulation factors Va and VIIIa along with protein C. Antiphospholipid antibodies are antibodies directed against phospholipid–protein complexes." (PMID 40018474, 2025). "Among White and Black women with adverse pregnancy outcomes, any thrombophilia was found to be more common among White women due primarily to Factor V Leiden mutation, whereas Black women were more likely to be diagnosed with protein S or antithrombin deficiencies." (PMID 38248552, 2024). "Additionally, we performed laboratory analysisfor thrombophilia (protein C, protein S, antithrombin deficiency, and Factor VLeiden mutation), and no abnormalities were found." (PMID 39618864, 2024). "The authors investigated a mix of established thrombophilias (ie, deficiencies of antithrombin, protein C and protein S, and antiphospholipid antibodies) as well as plasma levels of some coagulation factors (factor [F]VIII, FIX, and fibrinogen) and homocysteine." (PMID 36970734, 2023). "It is important to note that a current standard practice test panel of inherited and acquired thrombophilias consists of FV Leiden; prothrombin 20210A mutation; and levels of antithrombin, protein C, and protein S to detect an inherited deficiency and antiphospholipid antibodies." (PMID 36970734, 2023). "Protein S, a co-factor of protein C, is created in the liver and influences blood coagulation by increasing fibrinolysis; it is dependent on vitamin K. Low levels of protein S lead to a higher risk of thrombophilia, which itself is associated with a higher occurrence of thrombosis." (PMID 36837430, 2023). "Ninety-one percent (31/34) of children had unremarkable family histories, the grandfather of 1 patient had unknown thrombophilia and in 2 cases, TE occurred in 1 parent, each of whom was diagnosed with functional protein S (PS) deficiency." (PMID 37691772, 2023). "Furthermore, the prothrombin G20210A mutation and protein S deficiency were the most commonly detected hereditary thrombophilia in this study." (PMID 36388216, 2022). "However, a recent meta-analysis found a strong association between inherited thrombophilia (Factor V Leiden, G20210A polymorphism in the prothrombin gene, protein C and protein S deficiencies) and the increased risk of arterial ischemic stroke in adults." (PMID 35054824, 2022). "It is well known that familial protein S deficiency could lead to thrombophilia and venous thrombosis." (PMID 36078892, 2022). "Hypercoagulable disorders such as protein S deficiency may also present with ALCS related to thrombosis." (PMID 36192364, 2022). "However, the main inherited thrombophilia investigated at that time such as deficiency of antithrombin, protein C and protein S accounted for only 5- to 10% of the cases." (PMID 34956081, 2021). "Among inherited thrombophilias, AT deficiency was the first to be described; AT deficiency belongs to the high risk thrombophilias, along with protein C and protein S deficiencies and homozygosity or compound heterozygosity for factor V (FV) Leiden mutation and prothrombin mutation G20210A." (PMID 29907123, 2018). "PROS1 variants cause increased risk for thrombophilia due to protein S deficiency." (PMID 30487145, 2018).
thrombophilia (continued). "Thrombophilia was present in 23 patients (80%): in head, protein S deficiency (87%)." (PMID 26986141, 2016). "Moreover, there is a high incidence of thrombophilia in individuals with MA and PFO, in particular, in those with MTHFR, protein C, and protein S deficiency and the presence of thrombophilia increases the indication for closure." (PMID 25339937, 2014). "The remainder of the thrombophilia screen, including antiphospholipid antibodies, which may induce acquired protein S deficiency, yielded normal results." (PMID 21858020, 2011). "A thrombophilia work-up (lupus anticoagulant, anticardiolipin and anti-β2-glycoprotein I antibodies, factor II G20210A mutation, factor V Leiden mutation, anti-thrombin, protein C and protein S) showed low level of free protein S antigen (37% normal > 55%)." (PMID 20082713, 2010). "Protein S deficiency is a rare blood disorder which is a risk factor for thrombophilia." (PMID 16827935, 2006). "Protein S deficiency is an inherited cause of thrombophilia." (PMID 16827935, 2006). "Protein S deficiency, a condition that may be either inherited or acquired, may result in a hypercoagulable state and it predisposes affected individuals to thrombotic events." (PMID 15448814, 2004). "Thrombophilia prevalence varies: in Whites, factor V Leiden mutation accounts for 5% and prothrombin mutation accounts for 3%; lupus anticoagulants are found in up to 5% of individuals, whereas decreased protein C, protein S, and antithrombin activity occurs in less than 0.5% of cases." (PMID 36013523, 2022). "The most frequent ones are changes in the composition of the blood, such as acquired hypercoagulability states, mainly secondary to oral contraceptives, pregnancy, puerperium, but also inherited ones, as prothrombin mutation G20210A, Factor V Leyden, protein C and protein S deficiency." (PMID 32702831, 2020). "In an inherited thrombophilia, hypercoagulability caused by the deficiency of protein C and protein S predisposes an individual to increased risk of thromboembolism (TE) that could herald as a venous thromboemboilsm (VTE) in the leg, pulmonary embolism (PE), stroke, or Budd-Chiari syndrome." (PMID 31259110, 2019). "This article discusses the potential arguments for testing of inherited thrombophilia, including factor V Leiden mutation, prothrombin mutation, and deficiencies of antithrombin, protein C, or protein S and suggests some patient groups in childhood, which may be tested." (PMID 28352625, 2017). "In children with high-risk thrombophilia, the annual recurrence rates were 5.4% (95% CI, 2.6–10%) in children with antithrombin deficiency, but only 1.3% (95% CI, 0.3–3.8%) and 0.7% (95% CI, 0.08–2.4%) in protein C and protein S deficient patients, respectively." (PMID 28352625, 2017). "A thrombophilia status would be complementary to the risk score approach described here, as a functional test in the presence of clinical suscpiscion, in order to take into account rare mutations such as the one present in Protein S, Protein C or Antithrombin genes." (PMID 28750087, 2017). "It is important to measure protein S activity, specific activity, and antigen levels in patients with thrombophilia." (PMID 41567132, 2026). "Thrombophilia workup, including complement levels, immunoglobulins, protein C, protein S, and antithrombin III, was unremarkable." (PMID 41939548, 2026). "The mechanism by which myeloproliferative diseases lead to hypercoagulability is resistance to activated protein C and a reduction in free protein S levels leading to an increased activation of blood and endothelial cells." (PMID 40242703, 2025). "Deficiencies of natural anticoagulant proteins, including protein C, protein S, and antithrombin, represent another category of inherited thrombophilias relevant to SVT." (PMID 40428892, 2025).
thrombophilia (continued). "Hormonal status also matters: pregnancy increases fibrinogen, FVIII, vWF, and lowers protein-S activity; combined oral contraceptives shift the profile toward hypercoagulability." (PMID 41439002, 2025). "For patients in whom thrombophilia testing is warranted, assessment typically includes Factor V Leiden and FII G20210A and evaluations for protein C, protein S, and antithrombin deficiencies." (PMID 40429442, 2025). "Coagulation and thrombophilia testing (including antithrombin and Protein S levels) showed values within the reference range for neonatal age." (PMID 40669863, 2025). "Six patients (15%) had thrombophilia diagnosis: two with Factor V Leiden mutations, one with antiphospholipid syndrome, one with antithrombin III deficiency, one with Protein S deficiency, and one with sickle cell disease." (PMID 39974227, 2025). "Haematology was consulted, and extended thrombophilia testing was initiated, revealing low Protein S, with additional tests pending." (PMID 41393051, 2025). "The recommended test panel comprises antithrombin, protein C, protein S, Factor V Leiden, and the FII G20210A mutation, with antiphospholipid antibodies as the only marker for acquired thrombophilia." (PMID 40429442, 2025). "Thrombophilia screening should also be considered, or at least the evaluation of protein C, protein S, antithrombin III, Activated Protein C resistance, and, if necessary, homocysteine and D-dimer levels." (PMID 40842478, 2025). "Based on our centre experience, we recommend limited and targeted thrombophilia screening with Protein S (PS), protein C (PC), and anti-thrombin (AT) III during routine donor evaluation." (PMID 38463105, 2024). "If the patient has a deficiency in either protein C, protein S or ATIII, this will demonstrate that the patient has thrombophilia." (PMID 39534247, 2024). "Inherited thrombophilias include antithrombin III deficiency, protein C and protein S deficiency, activated protein C resistance due to factor V Leiden, and prothrombin gene mutation (factor II G20210A)." (PMID 39768679, 2024). "The ACOG practice bulletin explains that pregnancy itself is a hypercoagulable state with increases in fibrinogen and coagulation factors, decreased protein S levels, and decreased fibrinolysis." (PMID 39803112, 2024). "The risks of thrombophilia during pregnancy vary according to the etiology, antithrombin III deficiency and protein S and C deficiency are considered high-risk factors for thrombophilia during pregnancy." (PMID 39280542, 2024). "A suspicion of fetal stroke was raised and genetic testing confirmed inherited thrombophilia, with positive MTHFR A1298C and MTHFR C677T heterozygous gene mutations and Antithrombin, Protein S, and Protein C deficiencies." (PMID 37510971, 2023). "Genetic testing confirmed inherited thrombophilia, with positive PAI-1 4G/5G promoter and MTHFR C677T homozygous gene mutations and Antithrombin, Protein S, and Protein C deficiencies." (PMID 37510971, 2023). "Genetic testing confirmed inherited thrombophilia, with a positive MTHFR C677T heterozygous gene mutation and protein S and protein C deficiencies." (PMID 37510971, 2023). "Genetic testing confirmed inherited thrombophilia, with positive PAI-1 4G/5G promoter, MTHFR A1298C, and MTHFR C677T heterozygous gene mutations and Antithrombin, Protein S, and Protein C deficiencies." (PMID 37510971, 2023). "Genetic testing confirmed inherited thrombophilia, with a positive Factor V Leiden heterozygous gene mutation, MTHFR C677T homozygous gene mutation, and Protein S and Protein C deficiencies." (PMID 37510971, 2023). "Genetic testing confirmed inherited thrombophilia, with a positive MTHFR C677T homozygous gene mutation and Antithrombin, Protein S, and Protein C deficiencies." (PMID 37510971, 2023).
thrombophilia (continued). "The common inherited thrombophilias, like protein C, protein S, and AT III, were significantly associated with unexplained pregnancy loss, and protein S deficiency had the strongest association." (PMID 36873128, 2023). "Genetic testing confirmed inherited thrombophilia, with a positive PAI-1 4G/5G promoter homozygous gene mutation, MTHFR A1298C and MTHFR C677T heterozygous gene mutations, and Protein S and Protein C deficiencies." (PMID 37510971, 2023). "Genetic testing confirmed inherited thrombophilia, with a positive MTHFR A1298C heterozygous gene mutation and Protein S and Protein C deficiencies." (PMID 37510971, 2023). "A suspicion of perinatal stroke was raised and genetic testing confirmed inherited thrombophilia, with a positive PAI-1 4G/5G promoter homozygous gene mutation, MTHFR C677T heterozygous gene mutation, and Protein S and Protein C deficiencies." (PMID 37510971, 2023). "Genetic testing confirmed inherited thrombophilia, with positive MTHFR A1298C heterozygous gene mutation and Antithrombin, Protein S, and Protein C deficiencies." (PMID 37510971, 2023). "Genetic testing confirmed inherited thrombophilia, with positive MTHFR A1298C heterozygous gene mutations and Protein S and Protein C deficiencies." (PMID 37510971, 2023). "There was a positive family history of maternal thrombophilia (MTHFR A1298C, MTHFR C677T, PAI-1 4G/5G promoter, and Factor XIII (Val34Leu) heterozygous gene mutations and Protein S deficiency), treated with enoxaparin and acetylsalicylic acid during pregnancy." (PMID 37510971, 2023). "Genetic testing confirmed inherited thrombophilia, with positive Factor V Leiden and MTHFR C677T heterozygous gene mutations and Protein S and Protein C deficiencies." (PMID 37510971, 2023). "All nine children underwent testing for thrombophilia-related indicators, including antiphospholipid antibodies (aPL), protein C and protein S activity, antibodies to coagulation factors, and coagulation factor inhibitors." (PMID 37474910, 2023). "Genetic testing confirmed inherited thrombophilia, with positive Factor V Leiden and MTHFR A1298C heterozygous gene mutations, Activated Protein C Resistance V, and Antithrombin, Protein S, and Protein C deficiencies." (PMID 37510971, 2023). "Protein S is a glycoprotein created by the body that aids in the prevention of a hypercoagulable state." (PMID 37954832, 2023). "Genetic testing confirmed inherited thrombophilia, with a positive MTHFR A1298C heterozygous gene mutation and Antithrombin, Protein S, and Protein C deficiencies." (PMID 37510971, 2023). "Genetic testing confirmed inherited thrombophilia, with positive Prothrombin G20210A and MTHFR A1298C heterozygous gene mutations and Protein S and Protein C deficiencies." (PMID 37510971, 2023). "Genetic testing confirmed inherited thrombophilia, with positive MTHFR A1298C and MTHFR C677T heterozygous gene mutations and Antithrombin, Protein S, and Protein C deficiencies." (PMID 37510971, 2023). "Genetic testing confirmed inherited thrombophilia, with positive Prothrombin G20210A and MTHFR A1298C heterozygous gene mutations and Antithrombin, Protein S, and Protein C deficiencies." (PMID 37510971, 2023). "A similar approach was employed to identify downstream interactome of factors assessed in routine thrombophilia screens (factor V Leiden, prothrombin, antithrombin, protein C, protein S)." (PMID 34515987, 2022). "With regard to thrombophilia testing, only one patient (N3) was found to have a mildly reduced protein S level (43.8%, normal range 50–80%)." (PMID 36212667, 2022). "It has also been shown that there is a statistically significant difference between IBD patients and controls in thrombocyte volume, protein C, protein S, APC resistance, F1+F2 fragments, and tPA, which are associated with hypercoagulability." (PMID 35631302, 2022). "Extensive tests for thrombophilia markers (protein S activity, protein C activity, lupus inhibitors, homocysteine) were negative." (PMID 33918932, 2021).
thrombophilia (continued). "Smoking, long-term use of oral contraceptive (>5 years), and her decreased protein S antigen and anti-thrombin levels indicate her hypercoagulable state." (PMID 32195967, 2020). "As in nephrotic syndrome, hypercoagulability in protein-losing enteropathy is probably driven by the loss of antithrombin III and, to a lesser extent, protein C and protein S." (PMID 30651128, 2019). "In the case of antiphospholipid antibody syndrome, initiation of warfarin therapy can lead to thromboembolism and venous gangrene by similarly suppressing the levels of PC and protein S on top of a preexisting hypercoagulable state." (PMID 27264137, 2016). "The aim of this study was to determine the frequency of Protein C, protein S, AT III, and FVL mutation as a cause of thrombophilia in the patients with venous thromboembolism (VTE) and cerebrovascular accident (CVA)." (PMID 25674132, 2014). "Diagnostic workup of thrombophilia should include screening for FVL, protein C, protein S and AT III deficiency." (PMID 25674132, 2014). "Systemic tests such as Anti-thrombin III, deficiency of Protein C and Protein S, MTFR gen defect, and assays for thrombophilia are more valuable in the cases of widespread thrombophlebitis." (PMID 25780580, 2014). "Among the hereditary thrombophilia, 7 had reduced protein C levels, 10 had reduced protein S, 5 had reduced antithrombin levels, 3 were factor V Leiden heterozygotes, 3 were homozygous for MTHFR and in total 22 patients had at least one genetic marker." (PMID 24278436, 2013). "Patients with nephrotic syndrome are always in a state of hypercoagulability and hyperfibrinolysis, which could be caused by the increased synthesis of blood coagulation factors in liver, the increased consumption of antithrombin, and the decreased levels of protein S, protein C and plasminogen." (PMID 22738421, 2012). "The thrombophilia screen included functional chromogenic assays for antithrombin, Protein C and Protein S. Activated Protein C resistance was assessed with molecular confirmation of Factor V Leiden when indicated." (PMID 22084667, 2011). "Protein C (PC) and protein S (PS) determination is part of the thrombophilia investigation in patients with idiopathic venous thromboembolism (VTE)." (PMID 20482785, 2010). "Thrombophilia screening tested the presence of factor V Leiden, G20210A prothrombin gene mutation, antiphospholipid antibodies, factor VII, protein C, protein S and antithrombin activities." (PMID 21254740, 2010). "Testing for fibrinogen, in addition to well-recognized markers including APC-R, protein S and protein C, seems to be useful in young patients with primary venous thrombosis and in patients with a family history of thrombophilia." (PMID 21181065, 2010). "When present with other thrombophilias or when present in the homozygous form, protein S usually presents in neonates with purpura fulminans." (PMID 16968541, 2006). "Protein S gene abnormalities are the most common congenital predisposition to thrombophilia in the Japanese population, but not in the Caucasian population." (PMID 41567132, 2026). "Thrombophilia workup of functional assays for antithrombin III, protein S deficiency, polymerase chain reaction for factor V Leiden mutation, and testing for antiphospholipid antibodies and homocysteine levels revealed reduced protein S function and borderline protein C." (PMID 40084314, 2025). "The patient presented prominent hallucinations (Criterion A), which were evidently a consequence of the cerebral venous thrombosis secondary to primary thrombophilia, a fact confirmed by low plasmatic protein S levels and the presence of a homozygous MTHFR p.Ala222Val variant (Criterion B)." (PMID 40700101, 2025).